MYC (MYC proto-oncogene, bHLH transcription factor)
Diseases named in the same sentence as MYC in open-access papers (continued):
Sharing a sentence is not in itself a finding about the gene and the disease.
multiple myeloma (continued). "To investigate the role of host ARRB1 in anti-myeloma immunity, we utilized the well-characterized Vk*MYC syngeneic mouse model." (PMID 41373634, 2025). "Using Vk*MYC myeloma cells transplanted into wild-type and ARRB1 knockout mice, we show that ARRB1 deficiency in the host microenvironment promotes robust T cell infiltration and activation while reducing immunosuppressive myeloid populations." (PMID 41373634, 2025). "Among the proteins not previously linked to MM were three members (TAF5L, SUPT7L and SUPT20H) of the SAGA complex, a posttranslational regulator of MYC transcriptional activity that is important for myeloma growth." (PMID 38942927, 2024). "C1orf35, identified in multiple myeloma cell lines, acts as an oncogene promoting the G1-to-S cell cycle transition by modulating c-MYC expression." (PMID 39575189, 2024). "A frequency of regulatory T cells increases in the bone marrow of Vk*MYC myeloma-transplanted mice and their depletion promotes myeloma progression." (PMID 39474418, 2024). "In the Vk*MYC mouse model, myeloma cells spread in the bone marrow mainly 10-20 days after transplantation and then expanded in the spleen, leading to splenomegaly." (PMID 39474418, 2024). "Based upon the finding that MIDN promoted proteasome-mediated degradation of IRF4, and reports that IRF4 promoted c-Myc expression necessary for myeloma cell survival, we analyzed IRF4 and c-MYC levels in MidnKD/KD splenic B cells by immunoblot." (PMID 38625151, 2024). "A myeloma mouse model was performed by intravenous transplantation of Vk*MYC myeloma cells into XCR1-Diphtheria toxin receptor (DTR) knock-in or wild-type mice." (PMID 39474418, 2024). "The role of MYC has been established in the pathogenesis of multiple myeloma, given that its suppression has been shown to inhibit cell proliferation in multiple myeloma." (PMID 39355533, 2024). "The role of mTOR-dependent 4EBP1 phosphorylation in c-Myc-driven myeloma was examined in the mouse model Vk*MYC." (PMID 39482742, 2024). "Our finding was confirmed by a recent study where amplified MYC was shown to be effective in myeloma cancer." (PMID 38195844, 2024). "In this study we examined the effect of DIO on bone marrow immune cell composition and tumor growth in the Vk*MYC (Vk12653) myeloma mouse model." (PMID 38351079, 2024). "Here, we examined the effect of diet-induced obesity on bone marrow immune cell composition and tumor growth in a Vk*MYC (Vk12653) transplant model of multiple myeloma." (PMID 38351079, 2024). "Meanwhile, knockdown of ACSL4 can inhibit cell proliferation by regulating c-MYC in multiple myeloma." (PMID 39039611, 2024). "These include upregulation of E2F transcription factor-related gene expression and a MYC signature, pathways that have recently been identified as responsive to targeted therapies in myeloma." (PMID 39198400, 2024). "Drug efficacy studies in the Vκ*-MYC model predict single-agent drug activity in multiple myeloma, with a positive predictive value of 67% (4 of 6) for clinical activity, and a negative predictive value of 86% (6 of 7) for clinical inactivity." (PMID 39693340, 2024). "In the Vk*MYC mouse model, frequencies of activated/memory-phenotype CD44highCD62L- T cells were increased in myeloma-transplanted bone marrow." (PMID 39474418, 2024). "The Vk*MYC mouse myeloma cell line Vk12598, which grows in C57BL/6 mice, does induce osteolysis when injected systemically into mice, which is even more pronounced when the cells are injected intrafemorally." (PMID 36909335, 2023). "This process leads to duplicated sequence surrounding double stranded breakpoints, as previously reported in multiple myeloma, and often involving the MYC gene." (PMID 36658389, 2023). "This is exemplified by decreased HIF1α levels after MYC knock-down in multiple myeloma cells, and stabilization of HIF1α proteins after MYC overexpression." (PMID 37601651, 2023).
multiple myeloma (continued). "Multiple myeloma (MM) is a complex, frequently MYC-driven, hematological malignancy with a poorly understood etiology and inevitable progression." (PMID 38067212, 2023). "Nevertheless, myeloma specificity cannot definitively be proven without the use of tetramers and known myeloma antigens, which is acknowledged as a current limitation of the Vk*MYC myeloma model studied here." (PMID 36512425, 2023). "Multiple myeloma (MM) is a malignant plasma cell disorder in which the MYC oncogene is frequently dysregulated." (PMID 38067212, 2023). "This is consistent with the marked activation of MYC in UTX insufficient myeloma cells in our MM mouse model." (PMID 37198323, 2023). "Several drugs targeting MYC have been identified for Multiple Myeloma and have been evaluated in clinical trials." (PMID 37580667, 2023). "Since MYC was found as a central node or commonly downregulated gene/pathway in our RNA-Seq and proteomic data analyses, we investigated MYC’s role in FABP signaling in myeloma cells." (PMID 36880649, 2023). "In this study, PGG inhibited MYC transcription and promoted MYC degradation through a proteasome-independent pathway, thereby inducing G1-phase cycle arrest and apoptosis in multiple myeloma cell lines." (PMID 37375411, 2023). "Pharmacologic or genetic inhibition of FABPs result in reduced growth, decreased UPR and MYC signaling, decreased metabolism, and induction of apoptosis in myeloma cells in vitro." (PMID 36880649, 2023). "Subsequent ubiquitination and degradation of the transcription factors Ikaros (IKZF1) and Aiolos (IKZF3), which control myeloma survival and proliferation genes (e.g., MYC or IRF4), result in growth limitation and death." (PMID 37744361, 2023). "Selective targeting of ribosomal biogenesis by the small molecule inhibitor CX-5461 in MYC-dependent myeloma led to the inhibition of cell growth and reduction of MYC downstream target gene expression, thereby also overcoming drug resistance." (PMID 36969025, 2023). "Paìno and colleagues, in fact, highlighted the synergistic anticancer effects of PIM447 on a panel of different myeloma cell lines and observed a marked decrease in the phosphorylation of c-Myc at S62 and a downregulation of MYC mRNA levels." (PMID 36902175, 2023). "Inhibitors of translation initiation, such as rocaglate scaffold inhibitors, were shown to inhibit the oncogenic MYC-driven transcriptional program and abrogate myeloma growth in preclinical in vivo MM models." (PMID 38067212, 2023). "YB-1 expression, which was also determined to be downregulated upon MYC depletion, was already described as MYC-regulated, which in turn controls MYC mRNA translation and was demonstrated to be essential for multiple myeloma cell survival." (PMID 38067212, 2023). "In cellular assays 29 inhibits the expression of c-MYC, the growth of lymphoma, myeloma, and AML cell lines, and sensitizes cells to the growth inhibition, DNA damage, and apoptosis induced by olaparib." (PMID 37142850, 2023). "When looking at the LIN28-regulated oncogenes, analyses of CRISPR-engineered cells suggest that the LIN28/let-7 axis regulates MYC and cell cycle pathways in multiple myeloma and provides proof of principle for therapeutic regulation of MYC through let-7." (PMID 35806250, 2022). "This loss of euchromatin is particularly evident in promoters of oncogenic genes and in the super-enhancers driving c-MYC and other genes that are relevant for multiple myeloma proliferation." (PMID 36846090, 2022). "Of interest, anti-myeloma T cell immunity in the autologous transplant setting was further investigated by using the Vk*MYC murine myeloma model." (PMID 35563634, 2022). "This study aimed at determining the in vivo effects of TAK1-inhibitors in a Vκ*MYC multiple myeloma mouse model." (PMID 36435864, 2022).
multiple myeloma (continued). "Further, patients with high expression of OTUB1 show poor clinical outcomes in the c-MYC-dependent cancer multiple myeloma." (PMID 35159073, 2022). "Multiple myeloma, a malignancy of terminally differentiated plasma cells, is the second most common hematopoietic cancer and requires high c-MYC activity for progression, growth, and dissemination." (PMID 35159073, 2022). "Taken together, these results show increased dependency on the B cell lineage-specific transcription factors in blood cancers, with cancer-type-specific addiction to TCF3/IRF4 regulatory pathway in myeloma mediated by MYC expression." (PMID 35382456, 2022). "Multiple myeloma is a plasma cell-derived cancer, which requires c-MYC activity to progress and disseminate." (PMID 35159073, 2022). "We treated mice carrying Vκ*MYC multiple myeloma cells with the TAK1-inhibitors 5Z-7-oxozeaenol and NG25." (PMID 36435864, 2022). "Our study revealed that diet-induced metabolic and microenvironmental changes were insufficient to impact BM tumour burden in the Vk*MYC pre-clinical model of myeloma." (PMID 35908046, 2022). "In multiple myeloma and diffuse large B cell lymphoma, where high expression of MYC is a consequence of an active super-enhancer element proximal to MYC gene, BET inhibition induces strong MYC downregulation." (PMID 35408939, 2022). "Specifically, the activation of c-MYC is one of the key molecular events mediating disease progression from the early stage of monoclonal gammopathy of undetermined significance to multiple myeloma." (PMID 36846090, 2022). "Early studies suggested that JQ1 exerted potent antiproliferative properties in multiple myeloma via cell growth arrest and senescence in a c-MYC–dependent manner." (PMID 35349485, 2022). "Specifically, elevated c-MYC expression driven by translocation of the gene to the immunoglobulin or related enhancers is observed in 15%–50% of patients with multiple myeloma." (PMID 36846090, 2022). "In this study, we used the Vk*MYC MM model because it faithfully recapitulates the localization of the myeloma disease within the bone marrow as well as the clinical manifestation of the disease including bone damage (paralysis), renal failure." (PMID 35251496, 2022). "Blunting the oncogene c-MYC is one of the prime goals of experimental therapies in multiple myeloma and other c-MYC–dependent cancers." (PMID 36846090, 2022). "They induce cereblon-dependent degradation of the transcription factors Ikaros (IKZF1) and Aiolos (IKZF3), leading to transcriptional repression of IRF4 and MYC and resulting in myeloma cell apoptosis and stimulation of T and NK cell activity." (PMID 35563634, 2022). "Because multiple myeloma is a c-MYC–driven malignancy, several experimental therapies are being tested to reduce c-MYC levels." (PMID 36846090, 2022). "TCH-165 enhances MYC degradation and reduces cancer cell growth in vitro and in vivo models of multiple myeloma by enhancing apoptotic signaling, as assessed by targeted gene expression analysis of cancer pathways." (PMID 35625675, 2022). "TCF3 and IRF4 have previously been suggested as dependencies in myeloma and are part of the core regulatory circuitry, promoting tumorigenesis in cooperation with aberrant MYC activity." (PMID 35382456, 2022). "A common theme among several B-cell neoplasms, including multiple myeloma, is their dependence on the proto-oncogene c-MYC for progression." (PMID 36846090, 2022). "Overexpression of MYC is found in more than 70% of all human cancers, with a high prevalence in cancers of hematopoietic origin, such as acute lymphoblastic leukemia and multiple myeloma." (PMID 35625675, 2022). "Confirming its role in enhancing c-MYC activity, we found that elevated OTUB1 correlates with inferior clinical outcomes in the c-MYC-dependent cancer multiple myeloma, and overexpression of OTUB1 accelerates the growth of myeloma cells." (PMID 35159073, 2022).
multiple myeloma (continued). "The proto‐oncogene MYC is also associated with BET proteins; BET inhibitor downregulates MYC transcription leading to therapeutic effects on multiple myeloma and medulloblastoma." (PMID 34605158, 2022). "We found that MYC protein levels were rapidly reduced (within 4 h) in a concentration-dependent manner in the multiple myeloma cell lines, RMPI-8226, L363 and NIH-H929 cells, in response to 20S proteasome activation by TCH-165." (PMID 35625675, 2022). "As discussed in later chapters, scattered data exist on their role in multiple myeloma (MM) and in MYC-related malignancies." (PMID 34947882, 2021). "Possibly, the residual myeloma cells in MRD-positive patients on LEN maintenance therapy are resistant to LEN due to decreased CRBN burden, CRBN gene mutation, and c-MYC overexpression." (PMID 34638353, 2021). "Nonetheless, in further support of a role for the ISR-GCN2 pathway in myeloma survival, GCN2iB-sensitive HMCLs, as well as Vκ*MYC tumours (Vκ12598), undergo apoptosis upon treatment with GCN2iB." (PMID 34732728, 2021). "MYC is a master regulator of b-cell malignancies such as multiple myeloma, and its activation is known to deregulate mitochondrial function." (PMID 33916196, 2021). "MYC-driven deregulation of microRNAs represents a critical event in human malignancies, including multiple myeloma (MM)." (PMID 34503175, 2021). "IRF4 is also a direct target of MYC, generating an auto-regulatory circuit to support myeloma cell survival." (PMID 34680233, 2021). "In conclusion, we present a longitudinal single-cell depiction of tumour progression using the Vκ*MYC model of myeloma." (PMID 34732728, 2021). "Suppression of the expression of two other miRNAs that control the level of the MYC proto-oncogene, miR-126-5p and miR-29a-3p, is necessary for the survival and reproduction of myeloma cells." (PMID 34440124, 2021). "Downregulation of IKAROS and AIOLOS induces downregulation of MYC, a protein essential for myeloma proliferation and survival." (PMID 34864816, 2021). "PI is a therapeutic option for residual myeloma cells with refractoriness for LEN via c-MYC overexpression because PI has been reported to have a therapeutic effect in patients with c-MYC overexpression." (PMID 34638353, 2021). "A MYC activation signature was identified in the transition from premalignant conditions of plasma cell dyscrasias to symptomatic myeloma." (PMID 33562668, 2021). "Vκ*MYC also provided definitive genetic evidence on the involvement of the pro-inflammatory cytokine IL-18 in myeloma progression." (PMID 34149703, 2021). "Here, we report a disease spectrum-spanning, single-cell analysis of the Vκ*MYC myeloma mouse model." (PMID 34732728, 2021). "With a loss of function genetic screen, IRF4 is identified to be required for myeloma cell survival through activating its direct target MYC." (PMID 34680233, 2021). "It is also worth mentioning that a high level of MYC expression increases the resistance of myeloma cells to bortezomib by activating the pentose phosphate pathway." (PMID 34440124, 2021). "Critically, IRF4 was itself a direct target of MYC transactivation, generating an autoregulatory circuit in myeloma cells." (PMID 36045700, 2021). "This is one of several reasons why Vκ*MYC is widely considered in the myeloma community as the gold standard of mouse models." (PMID 34149703, 2021). "To further analyze the intratumoral heterogeneity in terms of YAP1/MYC expression, we collected the single-cell transcriptome data of 477 myeloma cells from GSE106218 which contained 9 MM samples and 3 paired EM samples." (PMID 35059315, 2021). "By implicating the upregulation of TIGIT (T-cell immunoglobulin and ITIM domain) on CD8 T cells, Vk*MYC has also contributed to our understanding of T cell exhaustion in myeloma." (PMID 34149703, 2021).
multiple myeloma (continued). "MYC is a master proto-oncogene with high implication in myeloma, accordingly 20–50% of patients with MM show MYC translocations and 15–20% show amplifications of the gene." (PMID 33916196, 2021). "Nonetheless, given the demonstrated importance of MYC dysregulation in myeloma biology and progression, future studies should seek to better understand the interplay between MYC and GCN2 in this disease." (PMID 34732728, 2021). "CPI-0610-mediated MYC inhibition induces G1 arrest and apoptosis in multiple myeloma resulting in tumor regression." (PMID 34372899, 2021). "CD86 overexpression induces molecular changes such as increased expression of integrin ß1 and ß7 and interferon regulatory factor 4 (IRF4), a transcription factor necessary for myeloma survival which directly targets MYC." (PMID 33634031, 2020). "A novel report demonstrated that the deletions linked with MYC actively generate SE to further augment MYC expression in multiple myeloma (MM), and the existence of MYC seRNA had been approved." (PMID 32278350, 2020). "A previously identified MYC G4-stablizer, which demonstrated cytotoxicity and senescence in myeloma cells, was discovered to induce endoplasmic reticulum stress and non-apoptotic cell death, pyroptosis." (PMID 33066043, 2020). "In multiple myeloma cells, c‐Myc protein level is maintained despite global decreased protein synthesis mediated by PERK‐eIF2α activation, owing to the upregulated activity of the MYC mRNA internal ribosome entry site upon ER stress." (PMID 32310340, 2020). "The DNA G-quadruplex (G4) present in the promoter of the MYC oncogene, commonly amplified in cancers, including multiple myeloma, represents a potential anti-cancer target." (PMID 33066043, 2020). "Oncogenic drivers of progression of monoclonal gammopathy of undetermined significance (MGUS) to multiple myeloma (MM) such as c-MYC have downstream effects on intracellular metabolic pathways of clonal plasma cells (PCs)." (PMID 32581232, 2020). "In MM pathogenesis, MYC activation and overexpression results from translocation, rearrangement or gain of the MYC locus, thus, it is an attractive target for myeloma therapy." (PMID 33066043, 2020). "Taken together, all of these results support contributions of both senescence and pyroptosis, in ER stress-induced myeloma cell death by the MYC G4 stabilizer, D089)." (PMID 33066043, 2020). "MYC protein overexpression is a feature of progression and adverse prognosis in multiple myeloma 42-45." (PMID 31956364, 2020). "A previous study found lower MYC exon 3 DNA methylation in human myeloma cell lines when compared with normal lymphocytes, which correlated with increased expression." (PMID 33374332, 2020). "The proto-oncogene MYC is often deregulated in ~70% of human cancers and over-expressed in multiple myeloma (MM)." (PMID 33066043, 2020). "Although these considerations need additional validations in context of PDAC, they are supported from clinical data in multiple myeloma, where MYC seem to be connected to a benefit of proteasome inhibitor‐based therapy." (PMID 33099868, 2020). "We have shown that BMPs induce growth arrest and/or apoptosis in myeloma cells via activation of the SMAD1/5 pathway which in turn leads to c-MYC downregulation." (PMID 32235336, 2020). "The small molecule was relatively potent in inhibiting multiple myeloma cell proliferation but was ineffective in tumor cell lines that had deleted the portion of the MYC promoter containing the G4 sequence." (PMID 32923678, 2020). "MUC1 will induce proliferation in multiple myeloma by signaling via a ß-catenin/TCF4 mechanism to drive MYC gene expression." (PMID 33634031, 2020). "BET inhibitors downregulate c-MYC transcription, suppress MYC-dependent target genes and inhibit myeloma cell proliferation." (PMID 33628735, 2020).